EDN1 (endothelin 1)
Diseases named in the same sentence as EDN1 in open-access papers (continued):
Sharing a sentence is not in itself a finding about the gene and the disease.
Cirrhosis (24 papers, 2009 to 2025). A chronic disorder of the liver in which liver tissue becomes scarred and is partially replaced by regenerative nodules and fibrotic tissue resulting in loss of liver function. "High levels of endothelin-1 are also associated with the development of portopulmonary hypertension in cirrhosis." (PMID 38396668, 2024). "Further research with simultaneous studies of the levels of endothelin-1 and big endothelin-1 in patients with cirrhosis are required to clarify the place of this molecule in the gut–liver axis." (PMID 38396668, 2024). "Plasma endothelin-1 (ET-1) levels also rise in patients with cirrhosis and intrapulmonary vascular dilatation." (PMID 39176346, 2024). "Endothelin 1 (ET-1) plays an important role in the regulation of intrahepatic PH in cirrhosis by stimulating HSC contraction in the liver, where the largest number of ET-1 receptors are located." (PMID 37761327, 2023). "Alcohol is furthermore responsible for the suppression of miR-199 in human endothelial cells that leads to steatohepatitis in patients affected by cirrhosis by inducing HIF1α and endothelin-1 (ET-1)." (PMID 31652839, 2019). "Plasma level of endothelin-1 (ET-1) is increased in cirrhosis and is substantially increased in patients with HPS." (PMID 24102057, 2013). "Activation of hepatic stellate cells (HSCs) plays an important role in the development of cirrhosis through the increased production of collagen and the enhanced contractile response to vasoactive mediators such as endothelin-1 (ET-1)." (PMID 21085652, 2010). "Moreover, earlier studies showed that endothelin-1 levels are higher in cirrhotic patients than in healthy individuals and increase with increasing severity of cirrhosis." (PMID 38396668, 2024). "miR-155 and -199, while not observed in our studies, were implicated in studies of rat liver cells and endothelial cells in humans in response to chronic alcohol insult, and lead to inflammation in cirrhosis through endothelin-1 (ET-1) and hypoxia-inducible factor-1α (HIF-1α)." (PMID 35126468, 2021). "Serum endothelin-1 (ET-1) levels are elevated in portopulmonary hypertension and associated with a poor outcome and have also been shown to correlate with HVPG values in patients with cirrhosis." (PMID 22720166, 2012). "ET-1 gene (EDN1) was significantly up-regulated, consistent with elevated levels of ET-1 peptide previously measured in PH and cirrhosis." (PMID 38860875, 2024). "Expression of the ET-1 gene (EDN1) was significantly up-regulated (adjusted P-value = 4.4 × 10−2, ln FC 0.63), consistent with elevated levels of ET-1 peptide previously measured in cirrhosis." (PMID 38860875, 2024). "Several authors, although they found an increased level of endothelin-1 in the blood of patients with cirrhosis, did not reveal its relationship with the severity of this disease." (PMID 38396668, 2024). "Perhaps this is due to the fact that the production of endothelin-1, which is reflected by the level of big endothelin-1, did not increase significantly in cirrhosis in contrast with its conversion into the active form." (PMID 38396668, 2024).
angina (23 papers, 2013 to 2025). "In contrast, peptides from the plasma of patients with progressive unstable angina suppress the secretion of endothelin-1 by HEPCs, while the secretion of both von Willebrand factor and tissue plasminogen activator was increased." (PMID 36837440, 2023). "Some role in these phenomena may also be played by endothelin-1 (ET-1), the level of which was increased in angina patients receiving 5-FU, likely due to its overproduction by ECs." (PMID 37221467, 2023). "The results showed that traditional Chinese medicine could improve angina [OR=1.34, 95% CI: 1.2 to 1.50], electrocardiogram (ECG), endothelin-1 (ET-1) levels, prolong exercise duration in treadmill tests, and reduce angina frequency per week compared with routine treatment." (PMID 23497135, 2013). "Both groups were then compared in terms of connective tissue growth factor (CTGF), endothelin-1 (ET-1), tumor necrosis factor-alpha (TNF-α), and some echocardiographic indices, weekly angina attacks and nitrate consumption before and after treatment." (PMID 35538296, 2023).
diabetic nephropathy (22 papers, 2012 to 2025). "Concerning the studies that correlate the EDN1 polymorphisms with plasma ET-1 concentration, it has been shown that in Chinese patients with diabetic nephropathy, the recessive allele A of EDN1 was connected with reduced plasma proendothelin-1 level." (PMID 38187330, 2024). "EDNRA itself has been implicated in diabetic kidney disease, where a study found that certain polymorphisms in the EDNRA and EDN1 gene acted protective against the development of the disease." (PMID 38153746, 2023). "Podocyte and Endothelial cell:In the pathological condition of high glucose, the abnormal renal expression of VEGF, angiopoietins, TGF- β, and endothelin-1 in early Diabetic nephropathy (DN) induces endothelial cell dysfunction and contributes to the disappearance of podocyte foot processes." (PMID 37538798, 2023). "In this study, the authors demonstrated that these improvements were specifically mediated by the inhibition of renal artery angiotensin II receptor type I/endothelin-1 axis, suggesting that much of the damage in diabetic nephropathy in this model was mediated via vascular effects." (PMID 37589053, 2023). "Using TNF as predictive marker and TGFB1 and EDN1 as monitoring markers might be a valuable strategy finding the subset of diabetic nephropathy patients benefitting the most from tacrolimus treatment." (PMID 28060893, 2017). "The molecular mechanism linking aldosterone and endothelin-1 in the development of diabetic nephropathy has not been completely elucidated." (PMID 23077601, 2012).
subarachnoid hemorrhage (22 papers, 2009 to 2026). A serious neurological disorder characterized by intracranial hemorrhage into the subarachnoid space. "Cerebral vasospasm caused by traumatic subarachnoid hemorrhage and facilitated by the vasoconstrictor endothelin-1 (ET-1) results in secondary cerebral ischemic edema after brain injury." (PMID 33505713, 2021). "The link between vasospasm and sensorineural hearing loss is directly evident in subarachnoid haemorrhage, which involves the release of vasoconstriction-inducing cytokines like interleukin-1, endothelin-1, and tumour necrosis factor." (PMID 31781229, 2019). "Other greenyellow hubs were associated with endothelin-1 signaling (PLBD1, MAPK14, CASP4), which is implicated in cerebral vasospasm following subarachnoid hemorrhage." (PMID 30836997, 2019). "High after the subarachnoid hemorrhage, Endothelin 1 gets into the central nervous system through the disrupted barrier." (PMID 20945816, 2010).
Myocardial fibrosis (21 papers, 2013 to 2026). "Fibrogenic growth factors, such as TGF-β1 and PDGF, as well as neurohormonal factors like angiotensin II and aldosterone, along with endothelin-1, play a pivotal role in the pathogenesis of myocardial fibrosis." (PMID 39834736, 2024). "Myocardial fibrosis was also elevated in cardiac tissue of SIRT3 knockout mice, as reported in other studies, and consistent with this, the expression of TGF-β, ATF4, and EDN-1 was inhibited by SIRT3 overexpression in AC16 cells and in neonatal rat cardiomyocytes." (PMID 32296036, 2020).
myocardial ischemia (20 papers, 2012 to 2025). A disorder of cardiac function caused by insufficient blood flow to the muscle tissue of the heart. "The primary constituent gastrodin mitigates myocardial ischemia–reperfusion injury through increased coronary flow, the suppression of endothelin-1 and pro-inflammatory cytokines (TNF-α/IL-6), oxidative stress reduction, and apoptosis inhibition." (PMID 40723404, 2025). "Endothelin-1 (ET-1) and its receptors are intimately involved in the regulation of this carrier-mediated NE overflow in protracted myocardial ischemia." (PMID 22792506, 2012). "Results of these studies show that hypoxia is involved in cerebral edema, tumorigenesis, myocardial ischemia and some genes including Endothelin 1 (EDN1), Erythropoietin (EPO) and Aldosterone synthase (CYP11B2) are reported as the key genes of hypoxia adaptation." (PMID 37735456, 2023). "This is manifested not only as inappropriately increased production of vasoconstrictors, such as endothelin 1, but also by dampened production of critical vasodilators, such as nitric oxide, prostacyclin, and neuregulins promoting the deepening of myocardial ischemia." (PMID 34205699, 2021). "The beneficial effect of fasudil has been demonstrated in a rabbit model of myocardial ischemia induced by an intravenous administration of endothelin-1, a canine model of pacing-induced myocardial ischemia and a rat model of vasopressin-induced chronic myocardial ischemia." (PMID 31174369, 2019).
psoriasis (20 papers, 2009 to 2024). An autoimmune condition characterized by red, well-delineated plaques with silvery scales that are usually on the extensor surfaces and scalp. "S1P produced by keratinocytes is involved in endothelin-1-mediated pruritus in the pathogenesis of psoriasis." (PMID 37072847, 2023). "While the level of endothelin-1 is usually regulated through various mechanisms, their expression appears to be altered in psoriasis patients." (PMID 21479272, 2011). "It is mitogenic to keratinocytes and a chemo-attractant to neutrophils Serum levels of endothelin-1 correlate PASI (Psoriasis Area and Severity Index) scores." (PMID 20049260, 2009). "It is well known that endothelin-1 causes nonhistamine-dependent pruritus in humans and that pruritus is an essential indication of psoriasis severity." (PMID 37072847, 2023). "Furthermore, endothelin-1 levels increase with psoriasis disease severity." (PMID 36012327, 2022). "Furthermore, endothelin-1 level appears to correlate with psoriasis disease severity." (PMID 21479272, 2011). "Compared to non-psoriatic controls, endothelin-1 expression appears to be higher in lesional skin and the blood of patients with psoriasis." (PMID 36012327, 2022). "Prostaglandin E2 (PGE2), endothelin-1 (ET-1) and endothelial leukocyte adhesion protein 1 (ELAM-1) have also been considered to be good candidates as itch mediators in psoriasis but future studies are required to confirm this hypothesis." (PMID 33467067, 2021). "Compared to individuals without psoriasis, the level of endothelin-1 appears to be increased in lesional skin and the serum of psoriasis patients." (PMID 21479272, 2011).
acute kidney injury (19 papers, 2009 to 2025). Sudden and sustained deterioration of the kidney function characterized by decreased glomerular filtration rate, increased serum creatinine or oliguria. "Vimentin KO mice do not have a renal phenotype under normal conditions, but with 3⁄4 reduction in renal mass, die of renal failure that appears to be mediated by abnormal vascular tone attributable to increased endothelin-1 expression and sensitivity." (PMID 27942003, 2016). "It has been indicated that endothelin-1 (ET-1) plays a role in the pathophysiology of various forms of renal diseases, including renal failure, renal hypertension, and CP-induced nephrotoxicity." (PMID 26457261, 2015). "In rats with renal failure, neutralization of TNF-α decreased NFκB activity that was associated with an improvement of nitric oxide released by reduction in renal transforming growth factor beta 1 and endothelin-1 production." (PMID 29636702, 2018).
lung carcinoma (19 papers, 2010 to 2025). "Aberrant activation of the EDN1 axis is now generally considered a common mechanism underlying the progression of various solid tumours, including ovarian, prostate, colon, breast, bladder, and lung cancers, which is an important adverse factor affecting the prognosis." (PMID 36053810, 2022). "Lung cancer cells stimulate the expression of endothelin-1 (ET-1) in astrocytes, activating PI3K/AKT and MAPK pathways." (PMID 41429896, 2025). "This research also demonstrated that IH promoted the proliferation and differentiation of endothelial cells by upregulating the expression of VEGF and endothelin-1, which accelerated the progression of lung cancer by inducing neovascularization in tumors." (PMID 38605948, 2024). "The endothelin-1 (ET-1) axis has been involved in lung cancer aggressiveness and suggested as an indicator of poor prognosis." (PMID 39443981, 2024). "Moreover, during the progression of lung cancer, the proportion of EDN1+CCL2+cECs decreases, while the proportion of IGFBP7+PLVAP+ECs significantly increases." (PMID 37187731, 2023). "In early-stage lung cancer nodules and metastatic lung cancer, IGFBP7+PLVAP+ tumor ECs were greatly amplified, whereas the proportion of extra-alveolar capillary ECs (cECs), EDN1+CCL2+ ECs, decreased." (PMID 37187731, 2023). "High levels of endothelin-1 (ET-1), its cognate receptor ETAR and its activating enzyme, the endothelin-converting enzyme-1 (ECE-1), have been reported in several cancer types, including lung cancer." (PMID 39443981, 2024). "In addition, although some EDN1(endothelin-1)-related BTS pairs and SHC1(Src homology 2 domain containing transforming protein)-related BTS pairs are shared in lung cancer tissue in current and former smokers, a considerable number of differing patterns are evident." (PMID 20628618, 2010). "In addition, although CAV1, SMAD7, BMP2, EDN1, and CXCL12 were not significantly different in the prognostic analysis in our study, they also play important roles in the occurrence and development of lung cancer." (PMID 34820377, 2021).
atrial fibrillation (18 papers, 2014 to 2025). A disorder characterized by an electrocardiographic finding of a supraventricular arrhythmia characterized by the replacement of consistent P waves by rapid oscillations or fibrillatory waves that vary in size, shape and timing and are accompanied by an irregular ventricular response. "Endothelin-1 has been reported to be associated with left atrial dilatation, fibrosis and atrial fibrillation." (PMID 31117937, 2019). "Big endothelin-1, the precursor hormone of endothelin-1, has also been shown to be associated with atrial fibrillation and many other cardiac diseases." (PMID 31117937, 2019). "Both angiotensin II and endothelin-1 have mitogenic effects on cardiac myocytes and play important roles in atrial structural remodeling in patients with structural heart disease and patients with atrial fibrillation." (PMID 30581499, 2018). "Endothelin-1 (ET-1) is a potent vasoconstrictor, mitogen and inflammatory factor that may contribute to development of atrial fibrillation (AF)." (PMID 30513109, 2018). "The role of plasma big endothelin-1 level in predicting atrial fibrillation after surgical septal myectomy in HOCM patients has not well been studied." (PMID 31117937, 2019). "Can the spinal cord stimulation (SCS) regulate the autonomic nerves through the endothelin-1 (ET-1) and nerve growth factor (NGF)/p75NTR pathways and thus inhibit the occurrence of atrial fibrillation (AF)?" (PMID 37808162, 2023).
cardiomyopathy (18 papers, 2013 to 2025). A disease of the heart muscle or myocardium proper. "Dysregulation of EDN1, a known vasoconstrictor, has been shown to cause CH and other cardiomyopathies." (PMID 36544188, 2022). "We found that only the sgRNA targeting the first exon of the fabp7a gene (fabp7aMJ‐e1), but not the other 3 lipodystrophy genes such as bscl2l, cidec, or edn1, restored the cardiac dysfunction in the bag3 cardiomyopathy model at 6 months of age." (PMID 40922543, 2025). "The increased levels of endothelin-1 (ET-1) and Lp-PLA2 have been linked to different heart conditions, including interferon-induced chronic active myocarditis and cardiomyopathy." (PMID 38167049, 2024). "Subsequent activation of AP-1 transcription factors upregulates endothelin-1, ultimately leading to increased expression of inflammatory cytokines, driving cardiomyopathy." (PMID 33322418, 2020). "These include a high positive selection on KAI14, KIF6 (both indicated in cardiomyopathy), and PDE11A (vasoregulation), as well as pathway enrichments for the renin-angiotensin system and the endothelin-1 pathway, identified in both WedAR and dN/dS analyses." (PMID 35177770, 2022).
fibrosis (18 papers, 2011 to 2024). the formation of excess fibrous connective tissue in an organ or tissue in a reparative or reactive process. "Endothelin-1 causes vasoconstriction and is involved in pulmonary vascular disease and fibrosis." (PMID 34550991, 2021). "Oxygen enrichment inhibited medial thickening, stenosis and fibrosis of pulmonary arterioles, and cytokine expression related with fibrosis (Col1α1, Col3α1, and hydroxyproline) and pulmonary vasoconstriction [endothelin-1(ET-1)] in HAH-exposed rats." (PMID 33488404, 2020). "Among fibrotic agents known to contribute to scleroderma, the role of endothelin-1 (ET-1) in SSc fibrosis has been well described." (PMID 27209208, 2016). "Silencing of the endothelial-specific histone methyltransferase SET domain containing 1 (SET1) could inhibit cardiac fibrosis and hypertrophy by repressing endothelin-1 transcription in response to chronic AngII treatment." (PMID 36481938, 2022). "Based on the diagnostic performance analysis of this RNAs panel, we concluded that the circulatory EDN1 Regulating RNAs panel could enable us to discriminate NAFLD/NASH cases from controls, and also NAFLD/NASH cases with early (F1, F2) from advanced Fibrosis (F3, F4)." (PMID 34828420, 2021).